FGF23 (fibroblast growth factor 23)
Diseases named in the same sentence as FGF23 in open-access papers (continued):
Sharing a sentence is not in itself a finding about the gene and the disease.
anemia (continued). "In this large-scale prospective cohort study, we investigated this relationship and examined whether high FGF23 levels increase the risk of incident anemia." (PMID 29740119, 2018). "In addition, we also showed that high serum FGF23 levels were significantly associated with an increased risk for the development of anemia even after a rigorous adjustment for multiple confounding factors." (PMID 29740119, 2018). "In fully adjusted multivariable Cox models, the risk of anemia development was significantly higher in the third (hazard ratio [HR], 1.66; 95% CI, 1.11–2.47; P = 0.01) and fourth (HR, 1.84; 95% CI, 1.23–2.76; P = 0.001) than in the first FGF23 quartile." (PMID 29740119, 2018). "Future studies are required to clarify the impact of RAS on FGF23-associated anemia." (PMID 29740119, 2018). "However, only few human studies have suggested a possible association between FGF23 and anemia in patients with CKD21–23." (PMID 29740119, 2018). "Additionally, other as yet unidentified factors may mediate the inverse association between anemia and total FGF23." (PMID 37752381, 2024). "Therefore, these factors may have contributed to the observed results from our multiple linear regression modeling evaluating associations between anemia and FGF23 moieties in this subgroup." (PMID 37752381, 2024). "The mechanism responsible for FGF23-associated anemia is unknown." (PMID 29740119, 2018). "Inhibition of FGF23 signaling in a mouse model of renal failure improved anemia by increasing erythropoietin levels, red blood cell counts, and bone marrow progenitors." (PMID 41157262, 2025). "In our cohort, study subjects with anemia had a higher prevalence of ESA use, and ESA use was associated with higher concentrations of total FGF23." (PMID 37752381, 2024). "We intend to evaluate the association of intact Fibroblast Growth Factor 23 (i-FGF23), a phosphaturic hormone that contributes to anemia of inflammation, with markers of iron homeostasis, inflammation, and bone mineral metabolism in acute pediatric infections." (PMID 39336155, 2024). "How FGF-23 and vitamin D play key roles in iron metabolism and the onset of anemia secondary to CKD will be elucidated in this paper." (PMID 39684548, 2024). "In our fully adjusted model, the magnitude of the effect of anemia on total FGF23 was similar to that of eGFR, and was greater than that of phosphate SDS for age, serum PTH, and active vitamin D use." (PMID 37752381, 2024). "Addressing anemia-related factors in CKD has unveiled potential avenues for modulating FGF23 levels." (PMID 38496297, 2024). "Paralleling the scenario observed in CKD, the elevation of FGF23 in AKI has been demonstrated to be mediated by factors such as anemia, inflammation, and metabolic pathways." (PMID 38496297, 2024). "In cross-sectional analysis, we observed that study subjects with anemia had higher circulating concentrations of total FGF23." (PMID 37752381, 2024). "Recent discoveries found a significant link between increased FGF23 levels and anemia development in CKD." (PMID 36831276, 2023). "These study findings suggest a physiological overlap between CKD-MBD and anemia through factors, such as FGF23." (PMID 37605118, 2023). "Previous studies have reported that FGF23 is a factor possibly associated with the overlap between CKD-MBD and anemia." (PMID 37605118, 2023). "Although these findings suggest common mechanisms between the regulation of mineral metabolism and osteocyte oxygen responses, the key cellular sensing mechanisms controlling bone FGF23 production during anemia remain poorly defined." (PMID 36650133, 2023). "A previous study showed that various physiological mechanisms are involved in FGF23 activity in anemia." (PMID 37605118, 2023). "In the present study, we extend the role of FGF23 in anemia from predialysis CKD patients to CHD patients." (PMID 37081846, 2023).
anemia (continued). "Due to the facts that FGF23 is stimulated by hypoxia/anemia and that Phd2 is known to be upstream of HIF activity, this gene was further explored." (PMID 36650133, 2023). "This phenomenon is postulated to occur due to an increase in the level and activity of FGF23 and decreased cleavage of the same, due to anemia as well as use of specific iron formulations." (PMID 36248222, 2022). "During studies defining the molecular mechanisms of ADHR, an anemia‐FGF23 linkage was discovered through the study of mice harboring an orthologous point mutation in the Fgf23 inactivating protease cleavage site." (PMID 35656701, 2022). "Men with anemia had higher serum levels of fibroblast growth factor 23 (iFGF23) (p < 0.001) and phosphate (p = 0.001) and lower serum levels of testosterone (p < 0.001) and estradiol (p < 0.001)." (PMID 35739404, 2022). "Previous clinical studies in humans and translational experiments in mice, as well as isolated osteoblast/osteocyte cells, have also shown that FGF23 is driven by anemia/hypoxia." (PMID 35656701, 2022). "Phosphate and fibroblast growth factor-23 (FGF23) have a close relationship, as both are related to the pathogenesis of anemia." (PMID 36432528, 2022). "Further anemia has been recognized as a very strong stimulator of Fgf23 mRNA levels in bone in vivo and in cells, and serum phosphate also drives Fgf23 production." (PMID 35656701, 2022). "Studying mice with CKD under dual conditions of treatment with exogenous iron on a genetic background of conditional Fgf23 deletion was another strength of this work, providing a unique opportunity to dissect phenotypes downstream of anemia." (PMID 35656701, 2022). "Elevated plasma FGF23 is an independent risk factor for CKD progression, anemia, and reduced hemoglobin (Hb); it is also associated with cardiovascular events." (PMID 34758731, 2021). "The iron absorbed during FC administration presumably contributed to anemia management and reduced FGF23 production." (PMID 34758731, 2021). "In this regard, it was worthy of noting that phosphorus was also related to BUN in our study and FGF23, the main phosphaturic hormone, was reported to be related to anemia in NDCKD." (PMID 34506574, 2021). "Erythropoietin and interleukin 1 beta (IL-1β), which are increased in condition of anemia and inflammation respectively, are two potent inducers of Fgf23 at the transcriptional level." (PMID 34149625, 2021). "These two circulating factors are produced in response to anemia and inflammation respectively, and induce cleaved FGF23 secretion in bone and bone marrow cells in rodents." (PMID 34149625, 2021). "Our goal was to test the correction of anemia and iron utilization on FGF23 production and its impact on mineral metabolism." (PMID 32476270, 2020). "Jointly, our data render a quite consistent picture of FGF23 in the clinical context of anemia in CKD, in which its interaction with iron metabolism holds a prominent rank." (PMID 32823844, 2020). "In a mouse model of CKD, this FGF23 antagonist peptide has been shown to rescue the prevailing anemia." (PMID 32982979, 2020). "Recent research has revealed a bidirectional relationship between fibroblast growth factor 23 (FGF23) and iron status, anemia, and inflammation, as well as the role of erythroferrone (ERFE) in iron homeostasis." (PMID 33392212, 2020). "In one of the recent studies, log-transformed total FGF23 was inversely associated with serum iron and TSAT and positively with hepcidin; and associations between FGF23 and anemia persisted after adjustment for ferritin and CRP." (PMID 33392212, 2020). "Elevated levels of phosphate, PTH, FGF-23, AGEs and uremic toxins, but also anemia and proteinuria can induce a systemic pro-inflammatory state." (PMID 31551803, 2019). "As for the indirect actions of FGF23, the interconnection between FGF23 and pro-inflammatory cytokines, such as in CKD, provides further insight on how FGF23 indirectly contributes to anemia." (PMID 31461904, 2019).
anemia (continued). "This review focuses on the latest advances in understanding the complex role of FGF23 in inflammation and anemia, and how these multi-directional relationships present significant insights into the pathomechanisms of CKD." (PMID 31461904, 2019). "The time to the development of anemia was significantly shorter in high FGF23 quartiles (P = 0.009 for first vs. second; P < 0.001 for first vs. third and fourth)." (PMID 29740119, 2018). "These unseen factors seem to have overwhelmed the effect of FGF23 on anemia in patients with a high disease burden." (PMID 29740119, 2018). "These factors include anemia, albuminuria, bone and mineral disorders, inflammation, and, more recently, fibroblast growth factor 23 (FGF-23)." (PMID 30518032, 2018). "Subgroup analyses showed that the use of RAS blockers can affect the relationship between FGF23 and the development of anemia." (PMID 29740119, 2018). "Anemia occurred in 48 (16.5%), 63 (21.6%), 91 (31.3%), and 93 (32.0%) patients in the first, second, third, and fourth quartile of FGF23, respectively (P < 0.001)." (PMID 29740119, 2018). "The results showed the consistent direction of the impact of FGF23 with respect to anemia in most stratified groups." (PMID 29740119, 2018). "In summary, the present systematic review of published RCTs suggested that FC reduces serum phosphate, i-PTH, and FGF-23 levels and improves anemia-related parameters, namely Hb, TSAT, and ferritin in patients with CKD stage 3–5D." (PMID 29291028, 2017). "The pathway by which low iron increases C-FGF23 expression is not clear but growing evidence points towards an involvement of the hypoxia-inducible-factor (HIF) pathway, activated by anaemia and hypoxia, in the increase in FGF23 gene expression." (PMID 26453792, 2016). "Prominent non-traditional risk factors include red cell related measures such as anemia, iron status and red cell distribution width (RDW), and markers of mineral metabolism, especially fibroblast growth factor 23 (FGF23)." (PMID 26079688, 2015). "When the effects of different parameters are excluded, determination of correlation between FGF-23 levels and anemia in the group determined to have high serum FGF-23 levels can support our thought." (PMID 25295189, 2014). "In this study, we aimed to demonstrate the correlation of FGF-23 levels with bone-mineral metabolism, anemia, and the treatment in dialysis patients.Methods." (PMID 25295189, 2014). "Anaemia and elevated FGF23 were more prevalent in BD children compared to LC children (P = 0.0003 and P = 0.0001 respectively)." (PMID 22465847, 2012). "FGF23 may aggravate anemia through direct mechanisms, such as suppressing erythropoietin secretion and inducing red blood cell apoptosis, and indirect mechanisms, including effects on iron metabolism via inflammatory cytokine induction." (PMID 41157262, 2025). "Preclinical studies show FGF23 inhibition improves erythropoiesis and iron metabolism, and phosphate control may reduce FGF23 and improve anemia, though balancing mineral homeostasis remains challenging." (PMID 41188188, 2025). "Notably, BAY 85–3934, a novel small-molecule oral HIF-PHI, has been reported to ameliorate anemia while reducing circulating FGF23 levels in a CKD murine model." (PMID 40281613, 2025). "Exogenous erythropoietin administration can increase total FGF23 concentrations in patients with CKD, so it is possible that ESA use may have at least partially mediated the association we observed between anemia and elevated total FGF23 concentrations." (PMID 37752381, 2024). "The “normal” ratio of functional to total FGF23 was preserved in our experiments, showing that the pregnant mouse is not compensating for the increase in FGF23 by reducing its functionality through increased cleavage, as in anemia, or by reducing FGF23 cleavage, as in CKD." (PMID 39452290, 2024). "FGF-23 is associated with CKD-MBD and anemia, suggesting that it could be the connecting factor between these conditions." (PMID 39684548, 2024).
anemia (continued). "As described later, FGF-23 promotes anemia and systemic inflammation." (PMID 39684548, 2024). "In adjusted analyses, anemia remained significantly associated with total FGF23, but not intact FGF23." (PMID 37752381, 2024). "In this cohort of pediatric patients with CKD, anemia was associated with increased total FGF23 levels but was not independently associated with elevated intact FGF23, suggesting possible effects on both FGF23 production and cleavage." (PMID 37752381, 2024). "Under this prism, i-FGF23 may contribute indirectly to hepcidin expression and anemia of chronic inflammation through cytokines induction." (PMID 39336155, 2024). "The goal of our study was to evaluate how anemia and anemia-related factors affect FGF23 levels; however, a bi-directional relationship may exist in which FGF23 also affects erythropoiesis." (PMID 37752381, 2024). "Finally, it is beyond the scope of this study to explore the mechanisms between anemia and serum Klotho, and we lack data on FGF23 and EPO to further explore the mechanisms involved." (PMID 36797683, 2023). "In addition to iron supplementation, treatments with the aim to increase EPO levels and, thus, correct anemia in CKD and the association with FGF23 have been investigated." (PMID 36831276, 2023). "However, both iron and phosphate correction as well as FGF23 levels reduction contributes to better outcomes by improvement in anemia and vascular calcifications, respectively." (PMID 36831276, 2023). "Malnutrition, anemia, accumulation of uremic toxins, activation of fibroblast growth factor 23 pathway (FGF-23) oxidative stress, and inflammation are other “non-traditional” risk factors in CKD that must be considered in computing the overall likelihood of developing CVD." (PMID 36978832, 2023). "In addition to iron, FGF23 itself has been demonstrated to induce anemia by intervening in erythropoiesis." (PMID 37081846, 2023). "Recent findings from the rodent experiments and clinical trials showed that treating anemia may be beneficial in reducing FGF23 levels." (PMID 36831276, 2023). "Since circulating FGF23 is increased by anemia and lowered by iron repletion, in our experiments, a targeted deletion of FGF23 from osteoblasts/osteocytes was used in concert with FC treatment to separate FGF23‐ versus FC‐driven effects." (PMID 35656701, 2022). "We previously reported that inhibition of FGF23 signaling rescues anemia in mice with CKD." (PMID 35813388, 2022). "Since serum FGF23 levels rise early in the course of CKD, elevated FGF23 may represent a novel contributor to the development of anemia in CKD." (PMID 36432528, 2022). "Furthermore, some treatments for anemia in CKD have potential effects on FGF23 and P concentrations, which can have an impact on the effectiveness of these therapies, raising hemoglobin levels." (PMID 36432528, 2022). "In a CKD mouse model, anemia increases FGF23 that can be rescued by treatment with EPO." (PMID 34536161, 2021). "Our hypothesis was that rescuing the prevailing anemia in a model of CKD would reduce circulating FGF23." (PMID 32476270, 2020). "In this cross-sectional study, we aimed to further characterize the role of FGF23 in anemia in CKD." (PMID 32823844, 2020). "It is possible that in patients with thalassemia, prolonged elevated serum FGF23 could aggravate anemia and prone them to cardiovascular and bone complications." (PMID 33198660, 2020). "However, further studies are necessary to investigate the disarranged processing events of FGF23 following conditions of inflammation and anemia, where C-terminal and intact FGF23 levels are elevated in the circulation at dissimilar magnitudes." (PMID 31461904, 2019). "Moreover, injection studies that employ the C-terminal FGF23 fragment disclose an inhibitory action, which reduces systemic inflammation and anemia in a mouse model of CKD." (PMID 31461904, 2019). "Our findings suggest that FGF23 can be a useful predictor of anemia in patients with CKD." (PMID 29740119, 2018).
anemia (continued). "The purpose of this study was, therefore, to further clarify the relationship between FGF23 levels and anemia in patients with CKD and to examine whether high FGF23 levels increase the future development of anemia, in a large-scale prospective cohort study." (PMID 29740119, 2018). "In conclusion, high serum FGF23 levels were associated with an increased risk for anemia in patients with nondialysis CKD." (PMID 29740119, 2018). "In addition, we demonstrated that high FGF23 level increased the future development of anemia in a longitudinal observation of a CKD cohort." (PMID 29740119, 2018). "FGF23 reduces renal production of erythropoietin and might thereby contribute to CKD-associated anemia." (PMID 29770125, 2018). "However, in our study, we did not determine any correlation between high serum parathormone levels and FGF-23 levels and anemia." (PMID 25295189, 2014). "However, in our final model, which included adjustments for ESA use and C-reactive protein, anemia remained associated with total FGF23 but not intact FGF23, suggesting that neither of these factors markedly confounded our observations." (PMID 37752381, 2024). "Lastly, our study is cross-sectional in nature and thus does not provide longitudinal insight as to whether anemia is associated with changes in FGF23 over time." (PMID 37752381, 2024). "Therefore, we could not assume for certain that low values of i-FGF23 directly promote hepcidin expression and subsequent FID and anemia in acute infections in clinical practice, which would render i-FGF23 a possible hepcidin agonist." (PMID 39336155, 2024). "However, in multiple linear regression modeling, anemia was not independently associated with intact FGF23." (PMID 37752381, 2024). "Therefore, our observation of an association between anemia and total FGF23 but not anemia and intact FGF23 suggests the effects of a factor associated with anemia that couples increased FGF23 transcription/translation with increased proteolytic cleavage." (PMID 37752381, 2024). "In this group, in adjusted analyses, anemia was associated with total FGF23, but not intact FGF23." (PMID 37752381, 2024). "Therefore, our modeling suggests that, in this CKD cohort, anemia may be as contributory to total FGF23 concentrations as kidney function and mineral metabolism parameters." (PMID 37752381, 2024). "However, a large-scale prospective cohort study found that high serum FGF23 levels were associated with an increased risk of anemia in patients with non-dialysis CKD." (PMID 36688811, 2023). "In addition, the involvement of FGF23 levels in anemia in CKD has also been suggested." (PMID 36432528, 2022). "Fourth, parathyroid hormone and fibroblast growth factor 23 might have a damaging effect on iron metabolism and confound the association between VD and iron circulation and anemia, but they were not measured in our study." (PMID 35745185, 2022). "Regarding CKD-associated anemia, murine in vivo studies suggest that FGF23 may have inhibitory effects on erythropoiesis and, in the CRIC study, higher FGF23 levels were independently associated with prevalent and incident anemia." (PMID 35237863, 2022). "In addition, anemia and increased FGF23 and EPO can also induce cardiac hypertrophy." (PMID 34362888, 2021). "Indeed, anemia clearly stimulates FGF23 mRNA production in bone in mice and humans with ADHR." (PMID 32476270, 2020). "Although it is not clear whether the increase in serum iron or the combination of elevated iron and reversal of anemia suppressed FGF23 in our study, it is likely that a major portion of the elevated FGF23 observed in the CKD mice could be attributed to defects in iron homeostasis." (PMID 32476270, 2020). "Consequently, anemia occurs in conditions of long-term increase in serum level of FGF23." (PMID 33198660, 2020).